PYY (peptide YY)
Description:
[Peptide YY]: Ligand for neuropeptide Y receptor type 1 (NPY1R) and neuropeptide Y receptor type 2 (NPY2R). Also binds NPY5R (By similarity). Receptor binding induces adenylate cyclase-inhibiting G protein-coupled receptor signaling, resulting in inhibition of cAMP production. Receptor activation by PYY also leads to an increase of intracellular Ca(2+) levels. This gut peptide inhibits exocrine pancreatic secretion (By similarity). Involved in the regulation of colonic antisecretory tone, and colonic contractility (By similarity). [Peptide YY(3-36)]: Is a NPY2R agonist involved in the down-regulation of appetite and food intake, probably acting on receptors located on proopiomelanocortin(POMC)-releasing and neuropeptide Y(NPY)- releasing neurons in the arcuate nucleus of hypothalamus. In NPY-releasing neurons, NPY2R activation by PYY(3-36) leads to membrane hyperpolarization and reduced release of the orexigenic neuropeptide NPY (By similarity).
Synonyms: PYY1; PYY-I
Tractability: Small molecule: a structure with a bound ligand is known. Antibody: its Gene Ontology location is reachable by antibodies, with high confidence; UniProt places it where antibodies can reach, with medium confidence; UniProt predicts a signal peptide or a membrane-spanning region.
Gene: Protein-coding gene on chromosome 17 (43,952,733 to 44,004,469, reverse strand). Ensembl gene ENSG00000131096.
Subcellular location: Secreted (Peptide YY)
Pathways (Reactome):
Signal Transduction: G alpha (i) signalling events; Peptide ligand-binding receptors
Gene Ontology:
Molecular function: G protein-coupled receptor binding; protein binding; receptor ligand activity; hormone activity; neuropeptide hormone activity; neuropeptide Y receptor binding
Biological process: negative regulation of eating behavior; feeding behavior; intestinal epithelial cell differentiation; neuropeptide signaling pathway
Cellular component: extracellular region
Genetic constraint (gnomAD): Loss-of-function variants: 12 observed, 10.43 expected, observed/expected ratio (o/e) 1.15, 90% interval 0.73 to 1.77. The upper end of that interval is the gene's LOEUF score, 1.77, which puts it in group 6 of 6, group 1 being the genes least tolerant of losing a copy. Missense variants: 141 observed, 136.53 expected, observed/expected ratio (o/e) 1.03, 90% interval 0.9 to 1.19. Synonymous variants: 66 observed, 61.24 expected, observed/expected ratio (o/e) 1.08, 90% interval 0.88 to 1.32.
Homologues: Orthologues: chimpanzee PYY (97% identical), macaque PYY (91% identical), dog PYY (76% identical), mouse Pyy (74% identical), rat Pyy (72% identical), guinea pig PYY (61% identical), zebrafish pyya (48% identical), zebrafish pyyb (44% identical). Paralogues in human: NPY (49% identical), PPY (30% identical).
Diseases named in the same sentence as PYY in open-access papers:
PYY is named in the same sentence as 129 diseases in open-access papers, as found by Europe PMC text mining. Sharing a sentence is not in itself a finding about the gene and the disease. The quoted sentences say what the papers report.
Obesity (250 papers, 2007 to 2026). Accumulation of substantial excess body fat. "Obesity is associated with reduced fasting and postprandial PYY levels, while T2DM shows blunted postprandial rises despite variable fasting levels." (PMID 41575482, 2026). "These behaviors impact hormonal secretion, including peptide YY and glucagon-like peptide-1, which regulate satiety and appetite, increasing the risk of obesity and obesity-related cardiometabolic diseases." (PMID 40507127, 2025). "Fasting PYY concentrations are inversely associated with BMI and are thus lower in people with obesity." (PMID 41043686, 2025). "For example, the effects of intraduodenal oleic acid to stimulate CCK, PYY, and pyloric pressures are diminished in individuals with obesity, compared with those with normal weight, associated with greater energy intake." (PMID 39785828, 2025). "The same was observed in humans, including obese individuals, suggesting a potential link between PYY deficiency and the development of obesity." (PMID 39016695, 2024). "The impact of PYY on inflammatory responses contributes to a lower risk of developing metabolic diseases associated with obesity." (PMID 39408213, 2024). "Obesity is associated with lower basal and postprandial concentrations of total ghrelin, lower postprandial concentration of total PYY, and lower postprandial hunger ratings, but large variations exist." (PMID 36416279, 2023). "The decreased secretion of GLP-1 and PYY is associated with the development of type 2 diabetes (T2D) and obesity, and upregulating their secretion as observed in gastric bypass surgery can lead to remission/improvement of both obesity and T2D." (PMID 35600607, 2022). "In the same line, deleting the production of PYY is linked with obesity and hyperphagia in mice, whereas prebiotic treatment is associated with increased level of PYY in the circulation." (PMID 35958993, 2022). "It is expected that the fermentation of RS to short-chain fatty acids (SCFA) will influence satiety hormones (GLP-1 and PYY) and lower the risk of developing obesity and metabolic signs of MetS." (PMID 34066330, 2021). "Whey protein was shown to increase the release of CCK and PYY and reduce ghrelin secretion, underlying a potential role in hunger suppression via reduced food intake and increased satiety in men and woman with obesity." (PMID 32121443, 2020). "Due to the role of PYY in appetite and energy expenditure, alterations in the expression and secretion of PYY influence the pathophysiology of obesity and hypertension which are important risk factors for CKD." (PMID 30781823, 2019). "Several gut hormones have been associated with appetite control and obesity, including peptide YY (PYY) and ghrelin." (PMID 30390699, 2018). "GLP-1 and PYY are incretins involved in nutrient absorption and energy storage and implicated in the pathogenesis of metabolic disorders, including obesity and type 2 diabetes." (PMID 26866366, 2016). "In summary, the association of fasting serum PYY concentration with obesity status and body fat measures was investigated among 2094 adults from the Canadian province of Newfoundland and Labrador." (PMID 24743402, 2014). "The purpose of this study was to investigate if fasting serum total PYY is associated with obesity status and/or adiposity at the population level." (PMID 24743402, 2014). "Several lines of evidence suggest that low circulating PYY concentrations predispose toward the development and maintenance of obesity." (PMID 24778627, 2014). "PYY reduces appetite and is associated with conditions such as obesity and anorexia nervosa." (PMID 40427747, 2025). "GLP-1 and PYY (peptide tyrosine-tyrosine) reduce the risk of diabetes and obesity." (PMID 40284028, 2025). "However, PYY can also slow down intestinal peristalsis, causing food to stay in the intestine for a longer time and increase energy absorption, thus leading to obesity." (PMID 40697558, 2025).
Obesity (continued). "However, leptin and insulin resistance caused by obesity result in reduced efficacy of satiety hormones like peptide YY and cholecystokinin over time, ultimately leading to decreased fullness." (PMID 40443725, 2025). "Interestingly, related genetic variants in PYY (encoding the ligand for NPY2R) have been associated with obesity-related traits solely in women." (PMID 39858569, 2024). "Gene variants in PYY are associated with changes in body weight and with obesity." (PMID 36983642, 2023). "Studies conducted on humans showed that PYY concentrations were lower in obese compared to normal weight individuals, suggesting that this appetite suppressing gut peptide is associated with the development of obesity." (PMID 36355134, 2022). "Also among these genes is the neuropeptide Y receptor type 2 (Npy2r) which is a receptor for both NPY and peptide YY, variants of which are associated with obesity." (PMID 33424545, 2020). "It is essential to clarify the role of PYY in the regulation of bone mass and strength because the use of PYY analogues in the treatment of obesity has the potential to cause long-term detrimental side-effects in the skeleton, including an increased risk of fracture." (PMID 31306808, 2019). "Gut hormones, such as PYY and ghrelin, are associated with appetite control and obesity." (PMID 30390699, 2018). "Low levels of PYY have been associated with higher BMI and obesity." (PMID 30390699, 2018). "Considering that very few cross-sectional studies with large sample sizes have been performed considering confounding variables and that the current results in the literature are controversial; there is a necessity to explore the association of circulating PYY with obesity at the population level." (PMID 24743402, 2014). "Similar to PYY, PP dysfunction in obesity reflects a hormone deficiency." (PMID 26237477, 2014). "Therefore the purpose of our study was to investigate the association of circulating PYY concentration with obesity status and body composition, measured by dual-energy x-ray absorptiometry, in a large population adjusting for major confounding factors." (PMID 24743402, 2014). "Although the effect size of the positive association of PYY with obesity in women is small, and potentially negligible, it may in fact represent a protective response against significant weight gain." (PMID 24743402, 2014). "However, after extensive analysis we have shown that circulating PYY is positively associated with obesity measures related to body fat in women." (PMID 24743402, 2014). "Low levels of PYY have been reported to be associated with higher BMI and obesity." (PMID 24743402, 2014). "Additionally, a recent study by our laboratory was also unable to detect an association of circulating PYY with obesity status (defined either by BMI or %BF) in a cohort consisting of young men." (PMID 24743402, 2014). "Conversely, obesity is associated with lower levels of PYY and greater bone mineral density." (PMID 22792209, 2012). "Moreover, endogenous PYY levels are reduced in obesity, suggesting that PYY deficiency may contribute to the pathogenesis of the condition." (PMID 41016636, 2025). "In the context of obesity the secretion of GI hormones may be impaired, as attenuated postprandial levels of GLP-1 and PYY have been characterized in some studies of obesity and negatively associated with appetite, length of postprandial satiety, and energy intake." (PMID 39142076, 2024). "Moreover, deleting the production of PYY is linked with obesity and hyperphagia in mice." (PMID 35958993, 2022). "Therefore the inaccurate measurement of adiposity and the misclassifications of obesity status could be the factor attributing to the contradictory reports concerning the association of PYY with obesity." (PMID 24743402, 2014). "Therefore investigating appetite regulating hormones, such as PYY, may provide valuable insight into the underlying mechanisms responsible for the development of obesity." (PMID 24743402, 2014).
Obesity (continued). "This group also proposed that endogenous PYY concentration was lower in obese rodents and humans, inversely associated with obesity-related phenotypes, and the administration of PYY could effectively reduce food intake and body weight independent of obesity status." (PMID 24743402, 2014). "PYY is reduced in obesity and shows impaired postprandial rises in T2DM, while PP is frequently elevated in T2DM." (PMID 41575482, 2026). "On the other hand, existing data consistently indicate that PYY levels, both fasting, and postprandial are lower in individuals with obesity compared to lean individuals." (PMID 41575482, 2026). "The elevated plasma levels of PYY, observed from the early stages of obesity development through the end of the intervention, strongly suggest a primary role of PYY in the ability of P. faecium to modulate food intake." (PMID 41566927, 2026). "In obesity and T2D, often there are blunted PYY, higher ghrelin, and, possibly, lower cholecystokinin (CCK) responses—all tilting the energy balance toward weight gain." (PMID 40871736, 2025). "Co-treatment strategies combining long-acting PYY analogs with GLP-1 receptor agonists hold promise as effective anti-obesity therapies." (PMID 41016636, 2025). "Propionate, on the other hand, reduces the risk of obesity by stimulating the release of glucagon-like peptide-1 (GLP-1) and peptide YY (PYY) and affects blood pressure by modulating renin release." (PMID 41488463, 2025). "Intraduodenal calcium enhances the effect of intraduodenal Trp to stimulate CCK, GLP-1, and PYY and suppress energy intake in males with obesity." (PMID 39785828, 2025). "In accordance with others, we too found that fasting PYY concentrations were low and postprandial PYY responses were attenuated in our sample of individuals with severe obesity (median BMI 42.8)." (PMID 39792913, 2025). "GPCR activated by butyrate as a signal molecule in the intestine also produces the endocrine hormones glucagon-like peptide 1 (GLP-1) and peptide YY (PYY), preventing obesity and insulin resistance induced by a HFD." (PMID 41365537, 2025). "Appetite hormones such as ghrelin, leptin, GLP-1, and PYY, are some of the most important body hormones that regulate appetite and prevent more appetite-related diseases such as obesity and diabetes." (PMID 41370490, 2025). "After bariatric surgery, circulating levels of PYY show a sustained increase, which correlates with reduced food intake and significant alleviation of obesity." (PMID 40500780, 2025). "An attenuated postprandial rise in PYY in people with obesity has been observed in additional studies." (PMID 41043686, 2025). "Although obesity and metabolic dysfunction are common in schizophrenia, the reasons that both asprosin, an orexigenic peptide, and PYY, an anorexigenic peptide, are low should be addressed as a separate research topic." (PMID 40075879, 2025). "Other studies have shown that serum PYY levels are lower in patients with obesity compared to healthy individuals." (PMID 40142315, 2025). "This study also showed that the postprandial rise in PYY is attenuated (resulting in a smaller area under the curve) in people with obesity despite their consumption of more energy during a buffet meal test." (PMID 41043686, 2025). "In obesity and T2D, there is often resistance to satiety signals and possibly blunted postprandial PYY or GLP-1 responses, contributing to hyperphagia." (PMID 40871736, 2025). "An example is “preload” shakes rich in certain amino acids or bitter tastants that can amplify GLP-1/PYY before a meal and reduce subsequent caloric intake (a strategy tested in obesity clinics)." (PMID 40871736, 2025). "A meta-analysis reported no statistically significant changes in circulating total ghrelin, acylated ghrelin, and total PYY or PYY3-36 after exercise-induced weight loss in adults with overweight and obesity." (PMID 39929932, 2025).
Obesity (continued). "Endocrine hormones, such as GLP-1, PYY, and leptin, produced by the combination of SCFAs and GPRs, can increase satiety and improve obesity." (PMID 40697558, 2025). "In contrast, the agonists of Y2 and Y4 receptors, high-affinity receptors for PYY and PP, respectively, are noted as a potential anti-obesity treatment." (PMID 41016636, 2025). "Compared with coconut oil-rich meals, corn oil has been shown to increase postprandial PYY concentrations in adolescents with obesity whereas a trend toward an increase in plasma PYY was observed compared with olive oil in normal weight adults." (PMID 40609691, 2025). "An attenuated postprandial PYY increase, and ghrelin suppression was also observed in Black adolescents and middle-aged adults with a range of BMI from healthy weight to obesity in 2 separate studies." (PMID 41043686, 2025). "Consistent with our observations in individuals of normal weight, calcium enhanced the effects of Trp to stimulate plasma CCK, GLP-1, and PYY, in a dose-dependent manner, in males with obesity." (PMID 39785828, 2025). "In the long term, dietary induced weight loss is accompanied by reduced concentrations of total PYY and CCK and increased concentrations of acylated ghrelin and these changes have been shown to precede weight regain in people with obesity." (PMID 39929932, 2025). ",10,33,37, 38, 39, 40 In the present study we show intestinal RGS expression is altered in obesity and associated with postprandial GLP-1 and PYY." (PMID 39142076, 2024). "Consistent with the positive effects of satiety, PYY levels were found to be heightened among individuals suffering from anorexia and diminished in those afflicted with obesity." (PMID 38725663, 2024). "The study, which included a relatively large number of people with severe obesity, supported previous evidence of BMI correlating negatively with fasting PYY and positively with fasting insulin." (PMID 38490484, 2024). "Bariatric surgery is now the most effective intervention for inducing weight loss among individuals with obesity, which likely reflects at least in part the associated elevated postprandial concentrations of GLP-1 and PYY." (PMID 39671480, 2024). "In this dataset of 205 participants spanning a wide BMI range, fasting GIP, insulin and PYY were shown to be important classifiers between participants with healthy BMI, overweight and obesity." (PMID 38490484, 2024). "LCK11 shows the potential to be used as a novel probiotic for preventing obesity by both promoting PYY secretion to inhibit food intake and regulating gut microbiota." (PMID 39501848, 2024). "Increases in total PYY have been reported in individuals with overweight and obesity after 60 min of MICT (at 60% V̇O2peak) or 60 min at 50% V̇O2max." (PMID 39263536, 2024). "Expectedly, initial studies exploring the potential of PYY as an anti‐obesity drug focused on peripheral administration of PYY(3‐36), which effectively reduces weight gain by inhibiting food intake in rodents." (PMID 39016695, 2024). "The development of obesity in mice fed WD was also reflected by the significantly increased plasma levels of the hormones leptin, peptide YY (PYY), resistin, and glucose-dependent insulinotropic polypeptide (GIP)." (PMID 38469142, 2024). "After RYGB, hormonal changes that promote WL are observed, mainly an increase in PYY levels and a decrease in ghrelin levels compared to obesity or pre-surgery subjects." (PMID 38398456, 2024). "Individuals with obesity exhibit lower fasting PYY(3‐36) levels and a reduced peak response, requiring double caloric intake to achieve levels equivalent to lean individuals." (PMID 39016695, 2024). "Fourteen studies compared basal concentrations of active PYY between individuals with obesity and controls." (PMID 36416279, 2023). "Ten studies compared basal concentrations of total PYY between individuals with obesity and controls." (PMID 36416279, 2023).